CD68 (CD68 molecule)
Diseases named in the same sentence as CD68 in open-access papers (continued):
Sharing a sentence is not in itself a finding about the gene and the disease.
tumor (continued). "High levels of CD68 are associated with a higher tumor grade, larger tumor size, Ki67 positivity, and other malignant features, which indicate tumor progression and aggressiveness." (PMID 35550532, 2022). "Recent studies have found that CD68 is overexpressed in tumor-associated macrophages (TAMs) and tumor cells." (PMID 35550532, 2022). "Few studies report that a high density of CD68-positive cells is associated with higher tumor grade, higher T stage, and poor prognosis." (PMID 36437290, 2022). "High expression of CD68 was associated with CD34+ cells in tumor and low 5-year DFS in 45 patients with LSCC from China." (PMID 36686729, 2022). "Because tumor-associated MΦ are suggested to be involved in tumor progression and/or aggressiveness, we investigated the distribution and density of CD68 (M1, pro-inflammatory) MΦ and CD163 (M2, anti-inflammatory) MΦ." (PMID 36230513, 2022). "A significant reduction in tumour-associated macrophages (CD68+), including the “pro-tumour” M2 phenotype (CD163+), together with lymphocytes (CD3+) was detected in LLC masses after treatment with both the stilbenes." (PMID 35892684, 2022). "For example, expression of transcripts encoding the tumor promoters Serpinb7, Aqp5, and Cd68 was induced by Src and suppressed by contact normalization." (PMID 35177067, 2022). "Along with reduced metastasis, we observed reduced infiltration of CD68+CD163+ tumor‐associated macrophages in the omentum of mice injected with HM‐β‐catenin shRNA cells." (PMID 35403834, 2022). "CD204 deficiency activated recruitment of CD68+ and F4/80+ macrophages into tumor mass by upregulation of MCP-1 in the CD204 KO bone marrow transplantation model." (PMID 36686729, 2022). "Analysis of 131 biopsies of Japanese PCa patients reveals a positive association between abundance of CD68+ macrophages infiltrating the tumor mass and both serum level of PSA and Gleason score." (PMID 36338516, 2022). "We found that high levels of CD68 were associated with many immune cells in the tumor microenvironment, such as monocytes, abundant B cells, CD4+ and CD8+ T cells, dendritic cells, macrophages, and neutrophils." (PMID 35550532, 2022). "It has been shown that iNKT cells can indirectly control tumor growth through targeting tumor-supportive, IL-6-producing, CD1d+ CD68+ tumor-associated macrophages (TAM)." (PMID 35784290, 2022). "Diffuse infiltrates of CD68+ macrophages were found to be associated with a shortened time-to-tumor recurrence, compared to focally infiltrating CD68+ macrophages (49.5 ± 27.6 vs. 15.8 ± 3.6, p = 0.002)." (PMID 35453901, 2022). "All subsets expressed high levels of Cd11b, Csf1r, Csf2ra, Cd14, Cd64 and Cd68 confirming their initial classification as tumor-associated macrophages and monocytes." (PMID 34381732, 2021). "Tumor-associated macrophages (CD68+), B cells (CD19+), and T cells (CD3+) were identified by immunohistochemical analyses of formalin-fixed paraffin-embedded tumor samples and quantified." (PMID 34205709, 2021). "In conclusion, our study demonstrated that PD-1H, which was predominantly expressed in CD68+ myeloid cells in ESCC tumor tissues, was positively associated with the infiltration levels of immune-activated cells." (PMID 34950702, 2021). "The results showed that CD58 expression was positively linked to the monocyte marker CD86, neutrophil markers CD66b and CD11b, tumor-associated macrophage (TAM) marker CD68." (PMID 34193136, 2021). "In HPV-HNSCC, which is highly infiltrated by lymphocytes, IFN-γ-induced PD-L1 on tumor cells and CD68+ tumor-associated macrophages (TAMs) and highly expressed PD-L1 by CTLs, are found located at the same site." (PMID 33562324, 2021). "Significance: Increased clustering of CD68+ TAMs and tumor cells was associated with worse overall survival for patients with metastatic ccRCC." (PMID 33882057, 2021).
tumor (continued). "We initially analyzed the association between the total CD11c+ DCs, CD68+ macrophages (included in both tumor and stromal compartments), and the clinical outcome." (PMID 35046943, 2021). "High levels of CCL5 and CD68 are associated with tumour size, degree of tumour invasion, lymphatic metastasis and pathological grading." (PMID 34638423, 2021). "In our meta-analysis, the pooled results showed both high CD68+ TAMs and M2-TAMs were associated with tumor necrosis and advanced nuclear grade." (PMID 34026635, 2021). "The high density of CD8+, CD3+, and CD68+ cells in the invasive frontin, frontout, and tumour core was associated with good prognosis by our models." (PMID 33915698, 2021). "Sampled surgical tumor specimens were analyzed by immunohistochemistry (IHC) for CD68-TAMs (tumor-associated macrophages), CD8-TILs (tumor infiltrating lymphocytes), PD-1-TILs, and PD-L1 tumor expression." (PMID 34572771, 2021). "Simultaneously, spatial analysis of T cells (CD3+), tumor-associated macrophages (CD68+), and aSMA+ cells revealed heterogeneity of immune and stromal cell densities." (PMID 34490110, 2021). "Tumor-associated macrophage-specific markers CD68 and CD163 were used as a marker of M1 and M2, respectively in this study." (PMID 33808480, 2021). "argues that patients with a high count of CD68+ tumor-associated macrophages have poorer surgical outcomes than those with a low count." (PMID 34458140, 2021). "In tumor nests, NE-low compared to NE-high tumors were associated with significantly increased densities of CD68+ (p = 0.048) and CD163+ cells (p = 0.024) in primary tumors, but not in LN metastases." (PMID 34200100, 2021). "Secondly, a subset of CD11c+ cells was identified as macrophages, either with the CD68 pan-macrophage marker or the tumor-associated macrophage marker CD163." (PMID 33803245, 2021). "Further analysis of multivariable Cox regression showed that CD163+ macrophage infiltration at the MI and tumor size were independent high-risk factors, whereas CD68+ macrophage infiltration at the CT and H. pylori positivity had a protective effect." (PMID 34926251, 2021). "Analysis of tissue sections obtained from colorectal cancer patients indicated a positive correlation between CD276 expression on tumor cells and CD68+ tumor associated macrophages (TAM) infiltration." (PMID 34290311, 2021). "Although most previous investigations used the CD68 pan-macrophage marker, two studies employing macrophage markers specific to M1 and M2 phenotypes found differential associations with patient and tumor characteristics as well as prognosis." (PMID 34066392, 2021). "Immunohistochemistry of the tumor-associated macrophage (TAMs) marker CD68 has started to reveal less hope for successful application of immunotherapy." (PMID 35366268, 2021). "A high CD163+/CD68+ TAM ratio at the tumor front was associated with worse survival in a study investigating Stage I–III CRC (n = 81), whereas no such association was observed when a high CD163+/CD68+ TAM ratio was found intratumorally." (PMID 34885098, 2021). "AKT3 expression in CAFs was significantly positively correlated with the proportion of α-SMA-positive CAFs (p < 0.001), number of CD68+ tumor-associated macrophages (p = 0.01), number of CD1a+ dendritic cells (p = 0.02), and number of CD3+ T cells (p = 0.03)." (PMID 33799788, 2021). "CCL5 from tumor cells or tumor-associated myeloid cells appears to license CXCL9 production almost exclusively from inflammatory CD68+ macrophages and CD11c+ DCs within the TME." (PMID 34354714, 2021). "The expression levels of CD68 protein, measured by IHC associated with advanced tumor stage, however this association was of borderline significance (p = 0.07)." (PMID 32019558, 2020). "In diffuse gliomas, the majority of MT-MMP-producing cells were IDH-mutated tumor cells, while CD68-immunoreactive microglia/macrophages constituted a much smaller proportion." (PMID 32872536, 2020).
tumor (continued). "Our finding of an association of CD68+/CD163+ TAMs with increased tumor cell proliferation is consistent with this protumorigenic function and argues in favor of a direct mitogenic, paracrine effect rather than a reduction in immune-mediated cytotoxicity." (PMID 32190817, 2020). "Histopathologic characteristics independently associated with plasma cfDNA concentration included CD68+ macrophage density (P = .01) and size of tumor vessels (P = .01)." (PMID 32140683, 2020). "CD68+ tumor–associated macrophages (TAMs), defined as macrophages located in or close by the tumor, were found to correlate with lymph node metastases and poor survival in HNSCC." (PMID 32602047, 2020). "CD68+-infiltrating cells in both the stroma and the tumor nests was significantly associated with PD-L1-positive tumors (p = 0.04 and p < 0.0001, respectively)." (PMID 32630659, 2020). "Based on these data, the aim of the current study was to assess the role of CD68+ tumor associated macrophages (TAM) in the development and progression of cHL." (PMID 32019558, 2020). "The impact of the spatial distribution of infiltrating immune cells differed by tumor morphology, but notably, in both tumor morphologies, a long distance between cancer cells and CD68+ macrophages as well as plasmacytoid DCs was associated with shorter OS." (PMID 33013928, 2020). "In an immunocompetent syngeneic rat tumour model, systemic treatment with MOv18 IgE was associated with pronounced infiltration of rat CD68+ monocytes and macrophages into lung-resident tumours." (PMID 33203088, 2020). "For example, after neoadjuvant chemotherapy, higher levels of epithelial lymphocytes (CD3+CD4+) and epithelial and stromal tumor‐associated macrophages (CD68+) were associated with better outcome in patients with NSCLC." (PMID 33072322, 2020). "The increased number of CD204+ cells and a high ratio of CD204+/CD68+ cells, indicative of the tumor-supporting polarization, were associated with a poor prognosis." (PMID 32194848, 2020). "GCB DLBCLs were also characterized by the expression of the KI67 proliferation marker, the tumor-associated macrophage (TAM) marker CD68, and cytotoxic and immune escape markers (GRB, PD-L1, and PD-L2)." (PMID 32444689, 2020). "CD68+ macrophage density was positively associated with tumor size (P = 0.022), whereas the density of CD57+ NK cells was much lower in EBVaGC samples with a tumor diameter greater than 5 cm (P = 0.026)." (PMID 33489884, 2020). "IHC analysis of 99 patients with NSCLC demonstrated that the number of CD68+ macrophages in the tumor islets was positively associated with OS, whereas the number of macrophages in the tumor stroma was negatively associated with OS." (PMID 33194645, 2020). "The study demonstrated that a high density of CD68+ TAMs in both TS and TN was significantly associated with larger tumor size (p = 0.036; p = 0.004)." (PMID 32607685, 2020). "The level of chronic inflammation, expression of PD1 and PD-L1, and biomarkers of total T lymphocytes (CD3), cytotoxic “effector” T cells (CD8) and tumor-associated macrophages (CD68) were evaluated using a scoring system as described in Material and methods." (PMID 31996725, 2020). "The expression level of two functional proteins on macrophages were detected including SIRPα, the ligand protein of CD47, and CD68, one of the markers of tumor-associated macrophages." (PMID 31139022, 2019). "The CD68+CD163+CD206+ macrophages (12%) were the least associated with tumor cells within this range." (PMID 31477692, 2019). "Treatment with MOv18 IgE was associated with the histological evidence of tumour infiltration by CD68+ human monocyte-derived macrophages, suggesting that these were recruited as a part of IgE-mediated anti-tumour functions." (PMID 31544825, 2019). "A variety of inflammatory cells reportedly infiltrates UC, including CD8+ TILs, tumor-infiltrating neutrophils and CD68+ tumor-associated macrophages." (PMID 31683784, 2019).
tumor (continued). "The density and location of tumour-associated rat CD68+ macrophages in tumours from rats treated with vehicle control, rat MOv18 IgG and rat MOv18 IgE were studied by IHC and flow cytometric analyses of freshly isolated tumour-bearing lung tissues." (PMID 31544825, 2019). "Analysis of CD68 expression using IHC confirmed the validity of our results and promoted the inflammation induced by tumor-associated macrophage as an underlying tumorigenesis mechanism in this cancer." (PMID 31552092, 2019). "In the tumor microenvironment of HPV-positive HNSCC, multiple cells, including a mixture of epithelial-derived tumor cells, and recruited CD68+ tumor associated macrophages (TAMs) have the ability to express PD-L1 protein." (PMID 31001266, 2019). "Some studies have suggested that PD-L1-positive tumors had prominent immune cell infiltration in CCA, such as CD3+ TILs (represent overall T cells), CD8+ TILs (represent cytotoxic T cells), and tumor-associated macrophages (TAMs) (CD68+, CD163+)." (PMID 31620360, 2019). "Staining of CD68, a pan macrophage (and tumor-associated macrophage) marker, suggestive of M1 type macrophages, was increased in progressive/persistent lesions (p ≪ 0.001 in the concordant set)." (PMID 31015447, 2019). "Macrophages present in tumours (tumour-associated macrophages or TAMs) exhibit M2 phenotype and are capable of expressing CD68 and CD163." (PMID 31186031, 2019). "Previously, it has been shown that PD-L1 and Galentin9, the ligands of PD1 and TIM3 respectively, were primarily expressed on tumor cells and CD68+ tumor associated macrophages (TAMs) in HCC that promoted immune escape." (PMID 31783783, 2019). "Tumor-associated macrophages are often identified by the immunophenotype CD68+ CD14+ and the number of macrophages correlates with tumor growth and prognosis." (PMID 31491903, 2019). "When the distance was extended to within 10–20 μm, the CD68+IRF8+ macrophages (47%) remained the major population associated with tumor cells." (PMID 31477692, 2019). "We previously observed the increased number of MMP-2 coupled CD31+ cells and CD68+ tumor associated macrophages (TAMs) at the invading front of ALTS1C1 tumors." (PMID 31106146, 2019). "TILs and CD68+ TAMs are associated with multiple tumour characteristics and patient survival in HCC." (PMID 31170995, 2019). "Most studies identify tumor-associated macrophages (TAMs) using markers (e.g., CD68) expressed by macrophages and other mononuclear phagocytes, such as monocytes." (PMID 31714922, 2019). "Tumor-associated macrophages (TAMs), which closely resemble the M2-polarized, are generally characterized by the expression of cell surface marker CD68." (PMID 31528120, 2019). "An immunoregulatory-rich tumor microenvironment was associated with lower mean of CD68+ pSTAT1+ cell numbers (mean 163 cells/mm2 for FOXP3+/GrB ratio >1.5 vs. mean 270 cells/mm2 for FOXP3+/GrB ratio ratio <1.5, p = 0.028, Mann-Whitney test)." (PMID 31481738, 2019). "By contrast, either CD163 or CD68 expression at tumor stroma was insignificantly associated with MCTC ratio." (PMID 30927925, 2019). "Previously, associations were reported between the MVD and the presence of tumour-associated macrophages (CD68+ cells, and CD68+CD163+ cells)." (PMID 31337000, 2019). "Density of CD68+ tumor-associated macrophages (TAMs) was higher in NCT-NSCLCs than in non-NCT-NSCLCs and was significantly higher in NCT-SCCs than in non-NCT-SCCs." (PMID 29871672, 2018). "The association between CD68+ macrophage number and age, gender, tumor location, histological grade, tumor stage, tobacco and alcohol consumption and HPV status was evaluated in both the intra-tumoral and stromal compartments of 110 HNSCC samples." (PMID 29541395, 2018). "For tumor-associated macrophages typically the CD68(+) M1-polarized phenotype is associated with tumor-suppressing properties indicating that a higher density of this population compared to the M2 type is beneficial." (PMID 29535336, 2018).
tumor (continued). "High levels of CCL5 and CD68 are associated with tumor size, degree of tumor invasion, lymphatic metastasis, pathological grading, and tumor thrombus, but are unrelated to patient age and gender." (PMID 29772686, 2018). "CD68 is a heavily glycosylated glycoprotein that is highly expressed by macrophages and is recognized as a marker for tumor-associated macrophages." (PMID 29573739, 2018). "The current study reveals an association between tumor size (T-status) and parameters of malignancy (L-status, grading) with the Gal3/CD68 ratio." (PMID 29284429, 2017). "In the LLC model, CB-1158 treatment caused an increase in CD8+ T cells in the tumor, as well as a decrease in CD68+ macrophages, compared to vehicle-treated controls." (PMID 29254508, 2017). "High p65 expression in CD68+ macrophages was seen at the inner invasive compartment of the tumor-associated stroma." (PMID 29062041, 2017). "p65KO mice implanted with GBM had statistically significant cellular reductions in CD45+ leukocyte, macrophage (F4/80+), tumor-associated macrophage (CD68+), MDSC (Gr1+ CD11b+), and M2 macrophage (CD206+ or mannose receptor) populations." (PMID 29062041, 2017). "All the results indicated that CD68 and TAMs in tumor stroma were strongly associated with worse OS." (PMID 28427165, 2017). "Of interest, the few scattered S100 positive cells with dendritic features were also positive for CD68, and thus believed to represent tumor-associated macrophages." (PMID 28343447, 2017). "Generally speaking, CD68 is the best established marker of tumor associated macrophages (TAMs), it is expressed on both M1 and M2 phenotypes." (PMID 28549420, 2017). "For example, in some studies, CD68+ Mφs were correlated negatively with patient prognosis; whereas, we and other groups have shown that GC patients with a high tumor-associated macrophage (TAM) count had better outcomes than those with a low TAM count." (PMID 28202073, 2017). "CD68 was used as a marker of tumor associated macrophages (TAMs) in most papers included in a meta-analysis and was highly expressed on both M1 (tumor inhibiting) and M2 (tumor promoting) macrophages." (PMID 28076333, 2017). "Even though it is mainly the anti-inflammatory subpopulation of TAMs that has been suggested to promote tumour progression, the entire CD68+ TAM population was also found to be associated with poor prognosis in the present study." (PMID 28673320, 2017). "Preoperative diagnostic biopsies (n = 26) and tumor resection specimens (n = 34) of T1/T2 oscc patients were immunohistochemically analyzed for Gal3 and CD68 expression." (PMID 29284429, 2017). "We observed positive univariate associations between the number of CD68 cells and tumor grade (p = 0.019)." (PMID 27487262, 2016). "The macrophages present in tumors are generally considered as tumor-associated macrophages (TAMs), which have a M2 phenotype and express CD68 and CD163." (PMID 26769084, 2016). "Results demonstrated that densities of CD68 and IL-13 in tumor stroma area were probably associated with the prognosis of patients." (PMID 26771842, 2016). "In conclusion, the results presented here indicate that a high density of either CD68+ or CD163+ TAMs in the tumor microenvironment of adult cHL is associated with poor survival." (PMID 27745550, 2016). "Over 5% tumor‐infiltrating macrophages identified by immunohistochemical staining for the CD68 antigen pick out patients at higher risk for PFS." (PMID 26758564, 2016). "Our results suggest that the mechanism of this effect is associated with the production of IDO1 by endothelial, tumor and CD68+ immune cells leading to tryptophan catabolism into kynurenine, which can be inhibited by MTH-trp." (PMID 27572319, 2016). "Conversely, high infiltrating density of CD68+ macrophages in tumor stroma indicated a decreased death risk (HR = 0.586, 95% CI: 0.378–0.908, P = 0.017) compared with patients with low infiltrating density." (PMID 27736796, 2016).